MTAP (methylthioadenosine phosphorylase)
Diseases named in the same sentence as MTAP in open-access papers (continued):
Sharing a sentence is not in itself a finding about the gene and the disease.
tumor (continued). "Using combined p16 and MTAP IHC, we were able to discriminate tumor areas with sustained p16-MTAP expression from tumor cell aggregates that were negative for both markers." (PMID 37894345, 2023). "MAT2A depletion led to impaired tumor growth and PRMT5 activity in MTAP-deleted cells." (PMID 37091983, 2023). "Deep deletions of chromosome regions containing FBXW7, CDKN2A, CDKN2B, and MTAP could be identified in the MPM693 patient-derived cell line and the corresponding tumor." (PMID 37345150, 2023). "In this review, we examine the current understanding of therapeutic vulnerabilities intrinsic to MTAP-negative tumours, focusing on MAT2A and PRMT5, which are receiving increasing attention in clinical development." (PMID 37795443, 2023). "Moreover, MTAP-ANRIL overexpression increased tumor cell proliferation, as indicated by the increase in ki67-positive cells, and significantly promoted tumor growth." (PMID 37277447, 2023). "The largest study was a pan-tumor study of CDKN2A and MTAP expression as a surrogate for 9p21.3 heterozygous or homozygous deletion, which confirmed our earlier HNSC/TME findings, specifically showing that 9p21.3 loss in HPV– HNSC was associated with immune-cold, CD8 T-cell depleted TME." (PMID 36395141, 2022). "In general, these results demonstrated that although MTAP/CDKN2AMUT RCC may be insensitive to targeted therapy, the high degree of tumor heterogeneity and immune-excluded TME reflected that MTAP/CDKN2AMUT patients could benefit from immunotherapies." (PMID 35979371, 2022). "An additional explanation suggested by our findings is that human GBM tumor environments are extensively infiltrated by MTAP-expressing non-malignant stromal cells." (PMID 34244484, 2021). "At last, FIDAS-5 treatment resulted in the occurrence of tumor cells with keratinization phenotype and involucrin expression in Xeno-76, but not in MTAP-WT C666-1 tumors." (PMID 34234122, 2021). "To assess the accuracy of the information and patterns gleaned from CNVseq, we conducted three separate examinations:A)We examined genome-wide gene expression data from these tumours (DASL HT12.4 array) to compare gene expression in CDKN2A, CDKN2B, MTAP and PTEN.." (PMID 31222134, 2019). "In addition to the focal deletion region, nearby regions within 9p21.3 also showed high frequency of deletion involving two tumor suppressors (CDKN2A, CDKN2B), MTAP and a cluster of type I IFN genes." (PMID 31311932, 2019). "Other genes that showed statistically significant correlation with disease stage were MTAP (rs = −0.30, p = 0.03), and SRM (rs = −0.27, p = 0.05), which tended to decrease the expression level with tumor stage, and OAZ3 (rs = 0.42, p = 0.003), which increased its expression with disease progression." (PMID 27433286, 2016). "Whether, the MTAP-ANRIL fusion transcripts detected in this study exert an oncogenic influence, if any, on tumor, remains to be determined." (PMID 26909863, 2016). "Our results show that MTAP has additional nonenzymatic functions that play an important role in its tumor suppressor function." (PMID 25387827, 2014). "The key finding of this study was that MTAP protein, but not enzymatic activity, was required for MTAP’s tumor suppressor effects on HT1080 cells." (PMID 25387827, 2014). "Taken together, these observations suggest that MTAP functions as a tumor suppressor gene independent of CDKN2A/ARF." (PMID 23840755, 2013). "In MTAP-negative tumor cells, the supplied MTA cannot generate adenine; hence conversion of the analog is not blocked." (PMID 19478948, 2009). "The results of the co-culture experiments with HF and MTAP-negative tumor cells, in the presence of the toxic analog DAP and the protective agents 5′-dAdo or MTA, are significant." (PMID 19478948, 2009).
tumor (continued). "In normal cells, but not in tumor cells lacking MTAP, MTAP cleaves the natural substrate, 5′-deoxy-5′-methylthioadenosine (MTA), to adenine and 5-methylthioribose-1-phosphate (MTR-1-P), which are then converted to adenine nucleotides and methionine." (PMID 19478948, 2009). "The discovery that MTAP is often absent in tumors led to proposals for a selective therapy that would inhibit or kill tumor cells, but leave host cells relatively unharmed." (PMID 19478948, 2009). "In MTAP-negative tumor cells, adenine is not produced from MTA or 5′-dAdo, and the cells are killed by the adenine analog." (PMID 19478948, 2009). "This distinct difference between normal MTAP-positive cells and tumor MTAP-negative cells led to several proposals for therapy." (PMID 19478948, 2009). "Once-dailyoral dosing of AM-9747 in mouse xenografts is well tolerated,displaying a robust and dose-dependent inhibition of symmetric dimethylationof arginine in MTAP-del tumor-xenografts and significant concomitanttumor growth inhibition without any significant effect on MTAP-WTtumor xenografts." (PMID 40102181, 2025). "The remaining 968 (IHC)/1226 (FISH) tissue samples were not interpretable because of a lack of unequivocal tumor cells, absence of MTAP staining in both cancerous and normal tissues, insufficient hybridization (FISH), or a lack of the entire tissue spot in the TMA section." (PMID 40227771, 2025). "Cytokines with anti-tumor properties including GM-CSF, IL-1α, IL-1β, IL-12, and IFN-γ were abundantly secreted in tumors without MTAP deletion, while anti-inflammatory cytokines such as RANTES, HGF, VEGF, IL-6, IL-8, and IL-9 were more represented in tissue with MTAP deletion." (PMID 41465382, 2025). "One possibility is that different cellular clones within the same tumour may carry distinct genetic and/or epigenetic alterations, which could result in variable MTAP expression—an observation that mirrors the heterogeneity noted in CDKN2A deletions by FISH." (PMID 40566743, 2025). "Indeed, there was no survival difference according to MTAP status when addressing different tumour types separately." (PMID 38350716, 2025). "The remaining 140/267 tissue samples were not interpretable because of a lack of unequivocal tumor cells, absence of MTAP IHC staining in both cancerous and normal tissues, absence of interpretable FISH signals, or a lack of the entire tissue spot in the TMA section." (PMID 40664803, 2025). "Furthermore, initial xenograft models suggest that first-generation PRMT5 inhibitors effective in MTAP-competent genetic backgrounds are cytostatic rather than cytotoxic because tumours regrew after treatment withdrawal." (PMID 39695328, 2025). "Here we have reviewed current pharmacological methods of targeting SAM production via MAT2A inhibition and direct PRMT5 inhibition (both of which reduce PRMT5-specific methylation reactions) and reported evidence for and against the selectivity of these treatments for MTAP-negative tumours." (PMID 37795443, 2023). "In conclusion, combined p16 and MTAP immunohistochemistry is a cost-effective surrogate for CDKN2A-MTAP genetic alterations that can be reliably used to detect homozygous deletions and visualize the spatial heterogeneity of the CDKN2A-MTAP gene complex within the same tumor sample." (PMID 37894345, 2023). "Moreover, we also found that MTAP may downregulate the expression of MMP2 and VEGFD in BC cells by inhibiting ODC activity, leading to the suppression of tumor angiogenesis." (PMID 35541910, 2022). "Importantly, using microdissected tumor samples and WGS, we detected the highest frequencies of homozygous deletions of the critical tumor suppressor genes CDKN2A, TGFBR2, TRAF3, and potential synthetic lethal target MTAP amongst NPC genomic reports thus far8–14." (PMID 34234122, 2021).
tumor (continued). "However, we did not observe a significant association between MTAP expression and other patients’ clinicopathological features, such as gender, age, or Karnofsky Performance Status (KPS), except for tumor location (p = 0.013)." (PMID 32093414, 2020). "As a result, tumor cells lack of MTAP could be potentially sensitive to inhibitors of the de novo purine synthesis pathway." (PMID 33335285, 2020). "However, MTAP-negative tumor cells are not able to produce AMP from the added MTA, so the purine analogs are metabolized and exert their toxic effects." (PMID 26751376, 2016). "There are potent inhibitors of MTAP which, if targeted to MTAP-positive tumor cells, could effectively make them phenotypically negative and susceptible to our treatment." (PMID 19478948, 2009). "In the second approach, Tisdale proposed that if serum were depleted of methionine by a methioninase, normal cells, but not MTAP-negative tumor cells, could be rescued by providing MTA, which is cleaved to MTR-1-P and leads to methionine synthesis." (PMID 19478948, 2009). "We describe a selective strategy to kill tumor cells lacking MTAP." (PMID 19478948, 2009). "To determine whether selective killing of tumor cells could be demonstrated with a different MTAP-negative tumor cell line, we co-cultured HF and MCF-7 for three days." (PMID 19478948, 2009). "Analysis of MTAP exons in tumours with 9p21–23 LOH did not detect deletions or sequence mutations." (PMID 15305192, 2004). "Therefore, our data suggest that the use of the MTAP inhibitor MTDIA in MTAP+/+ tumors would conserve the noncatalytic tumor-suppressive functions while still accumulating MTA that stimulates additional tumor suppressive functions through PRMT5 inhibition." (PMID 38000655, 2024). "However, tumor cells lacking MTAP are unable to convert MTA into adenine." (PMID 36913304, 2023). "Furthermore, another study revealed that MTAP deletion results in accumulation of the metabolite 2-methylthioadenosine and promotes the synergism between inhibitors of PRMT5 and of type I PRMT (i.e., GSK3368715) in PDAC, a tumor type in which MTAP is frequently deleted." (PMID 35406598, 2022). "Accordingly, we hypothesized that the tumor‐suppressive activity of MTAP is mediated through the MTA/PRMT5/protein dimethylation axis, and thus we identified those differentially symmetrically dimethylated proteins in response to MTAP alteration by mass spectrometric analyses." (PMID 35766227, 2022). "PRMT5 inhibitors might exert beneficial effects on tumor cytotoxicity but also disrupt the tumor immunosurveillance, possibly explaining why current PRMT5 inhibitors have no selectivity for MTAP‐loss tumors but instead are broadly anti‐proliferative." (PMID 35766227, 2022). "Although homozygous deletion of MTAP is associated with increased PRMT5 inhibitor sensitivity in some pancreatic organoids, broader examination of the impact of MTAP status across different tumour cells lines suggests that it is not a reliable biomarker of sensitivity to PRMT5 inhibition." (PMID 34680285, 2021). "Whatever whole-block or tissue microarray sections, the MTAP-positive tumor cells only ranged from 10% to 20% at most, which might not be isolated in the process of laser capture microdissection and therefore result in an underestimated gene ratio skewed toward homozygous deletion." (PMID 25426549, 2014). "Taken in total, these findings suggest that MTAP may exert its tumor suppressor effects via two different mechanisms; an enzyme-dependent mechanism that may involve the accumulation of the MTAP substrate MTA, and a nonenzymatic mechanism that predominates in HT1080 cells." (PMID 25387827, 2014). "Treatment with GSK3326595 led to marked suppression of tumor SDMA levels, irrespective of MTAP status." (PMID 40377999, 2025). "We have previously shown that such a near-complete concordance between MTAP IHC and FISH analysis does not apply to all tumor entities." (PMID 40227771, 2025).
tumor (continued). "The tumor cells were positive for AE1/AE2, calretinin, WT-1, D2-40, HEG1, EMA, BAP1, and MTAP and negative for carcinoembryonic antigen, MOC-31, Ber-Ep4, ER, PgR, TTF-1, claudin 4, and desmin." (PMID 36896044, 2023). "It has been demonstrated that the growth of MTAP-lacked tumor cells is abrogated by PRMT5 inhibition, making PRMT5 a synthetic lethal target for MTAP-lacked tumors." (PMID 37091983, 2023). "Homozygous and single copy deletions of the MTAP gene were observed in ESFT cell lines and primary tumour; homozygous deletions (but not single copy deletions) have previously been described with similar frequency to this study." (PMID 17533400, 2007). "Moreover, 12 cases with high, but not complete, MTAP expression (50%–99% of positive tumour cells) were also found; among them, six cases (50%) harboured a CDKN2A HD, notwithstanding preserved MTAP expression." (PMID 40566743, 2025). "Regardless of the method, MTAP deletion is detected in formalin-fixed paraffin-embedded (FFPE) tissue material, although the latest genetic techniques also enable the examination of free, circulating, tumor DNA from peripheral blood." (PMID 41465382, 2025). "However, in MTAP deleted cells, due to lack of adenine, PRPP is present at a high level and converts the analog to its toxic nucleotide, hence killing the tumor cell." (PMID 36572880, 2022). "If MTAP activity in serum were high enough to convert administered MTA (or another MTAP substrate) to significant levels of adenine, this might indiscriminately protect not just MTAP-positive host cells, but MTAP-negative tumor cells as well." (PMID 19478948, 2009).
adenocarcinoma (8 papers, 2022 to 2026). A common cancer characterized by the presence of malignant glandular cells. "While studies representing a lower rate of these mutations mostly contain adenocarcinoma histological type, the higher numbers of MTAP and CDKN2A/B alteration incidences in our case could be due to squamous NSCLC patients, who accounted for 1/3 of all patients." (PMID 40650126, 2025). "In an adenocarcinoma that was found to have homozygous deletion of CDKN2A, mTAP expression was lost in a subset of neoplastic cells." (PMID 35565429, 2022).
hematologic malignancies (4 papers, 2018 to 2024). "CDKN2A/2B and MTAP deletion frequency were the highest among the genes analyzed and their codeletion was also previously reported in solid cancers and hematological malignancies." (PMID 36601176, 2023). "Many solid tumours and hematologic malignancies lack expression of the MTAP enzyme, due to either deletion of the MTAP gene or methylation of the MTAP promoter." (PMID 30123503, 2018).
CNS tumors (3 papers, 2024). "TNG908 shows selectiveantitumor activity when dosed orally in mouse xenograft models, andits physicochemical properties are amenable for crossing the blood–brainbarrier (BBB), supporting clinical study for the treatment of bothCNS and non-CNS tumors with MTAP loss." (PMID 38595098, 2024). "With these findings, we can conclude that MTAP IHC is a reliable surrogate biomarker that shows high sensitivity and specificity for detecting CDKN2A HD in diffuse gliomas as well as other CNS tumors." (PMID 38109891, 2024).
gastro-intestinal tumors (3 papers, 2013 to 2025). "The purpose of this study is to investigate the prevalence and genomic landscape of MTAP-loss in advanced gastrointestinal (GI) tumors and investigate its role as a prognostic biomarker." (PMID 38330461, 2024). "This study investigated the prevalence and genomic landscape of MTAP-loss in advanced gastrointestinal tumors and its role as a prognostic biomarker." (PMID 38330461, 2024). "MTAP-loss overall occurred in 8.7% of the 5 GI tumors profiled (5203/59 657 tumors) and was balanced in patient age and gender." (PMID 38330461, 2024).
bacterial infections (1 paper, 2018). "Therefore, future studies will test whether MTA nucleosidase inhibitors and MTAP inhibitors could be harnessed to combat bacterial infections and improve clinical outcomes." (PMID 29866910, 2018).
cardiovascular diseases (1 paper, 2025). "To probe the translational relevance of MTAP in cardiovascular diseases, we investigated large-scale transcriptomic and proteomic datasets." (PMID 41332607, 2025). "At single cell level, we observed these significant increases in vascular cells isolated from HCM and DCM heart including in vascular smooth muscle cells, fibroblasts, among other cell types – suggesting dysregulation of MTAP expression in cardiovascular disease processes." (PMID 41332607, 2025).
MTAP also shares sentences with these, for which no sentence is quoted: neuroendocrine neoplasm (4 papers); acute lymphoblastic leukemia (3); adenosquamous carcinoma (2); anaplastic astrocytoma (2); cholangiocarcinoma (2); Coronary Artery Disease (2); gallbladder adenocarcinoma (2); head and neck carcinoma (2); lymphoepithelial carcinoma (2); nodular melanoma (2); pleomorphic xanthoastrocytoma (2); sarcomatoid carcinoma (2); acute leukemia (1); aortic aneurysm (1); Behavior Problems (1); benign prostatic hyperplasia (1); benign tumours (1); biliary tract cancer (1); bladder (1); blue nevus (1); bone cancer (1); cervical cancer (1); chondrosarcoma (1); combined immunodeficiency (1); cutaneous melanoma (1); diabetes (1); dysplastic nevi (1); endometrial carcinoma (1); epidermolysis bullosa (1); esophageal adenocarcinoma (1).
A further 33 diseases each share a sentence with MTAP in 1 paper.